IL6 (interleukin 6)
Diseases named in the same sentence as IL6 in open-access papers (continued):
Sharing a sentence is not in itself a finding about the gene and the disease.
Hypertension (continued). "Yet, myelomonocytic cells and monocytes attached to the vascular endothelium release pro-inflammatory cytokines such as IL-6 which is independently associated with hypertension." (PMID 37854465, 2023). "Hypertension is also associated with a pro-inflammatory state, as evidenced by increased levels of Angiotensin II, chemokines, cytokines, Interleukin-6 (IL-6) and tumour necrosis factor (TNF)." (PMID 37796879, 2023). "In this context, IL-6 is an important cytokine that polarizes T-helper lymphocytes and leads to the immunological imbalance associated with high blood pressure." (PMID 37242615, 2023). "Our findings showed that the effect of IL-6 genetic variants on the essential hypertension phenotype was small." (PMID 37920615, 2023). "Smoking, drinking, hypertension, prolonged duration of mechanical ventilation and intensive care unit stay, and IL-6 on POD2 were independent risk factors for pneumonia after cardiovascular surgery." (PMID 35794529, 2022). "Clinical trial data show that elevated plasma IL-6 concentrations are tightly associated with the severity of refractory hypertension and the six-year risk of death." (PMID 36703963, 2022). "The CC genotype was associated with higher levels of serum IL-6 (23.5 pg/ml vs. 10.5 pg/ml for the other genotypes; P = 0.006), even after adjustment for age, hypertension and coronary artery disease (estimate: 13.92, 95% CI 2.16–25.68, P = 0.021)." (PMID 36337884, 2022). "Inflammation as a potential contributor to genesis of GH15 and the role of IL-6 in causation of hypertension during pregnancy are well documented." (PMID 35821033, 2022). "In conclusion, our findings show that the -IL-6-572 C/G and -IL-6-174 G/C polymorphisms are linked to the onset of hypertension." (PMID 36518119, 2022). "Hypertension is also linked to a pro-inflammatory state with studies demonstrating significant elevation of inflammatory markers such as interleukin-6 (IL-6) and c-reactive protein (CRP) in hypertensive subjects." (PMID 36126060, 2022). "For instance, elevation in IL-6 has been associated with pre-eclampsia, gestational diabetes, and hypertension." (PMID 36142193, 2022). "IL-6 is a key regulator of the hepatic synthesis of acute phaseproteins including C-reactive protein (CRP) which has been linked to hypertension and cardiovascular disease." (PMID 37323554, 2022). "Apigenin improves hypertension and cardiac hypertrophy in spontaneously hypertensive rats, which are associated with the downregulation of inflammatory factors, such as IL-1β, IL-6, and iNOS in the hypothalamic paraventricular nucleus." (PMID 35955548, 2022). "An early study of IL-6 in the elderly found that elevated levels of plasma IL-6 with age were associated with the prevalence of heart attack, high blood pressure, cancer, and functional disability (3 indexes of daily living were measured)." (PMID 35821823, 2022). "A nested case–control study of 400 normotensive women indicated that the risk of developing hypertension during follow-up increases with higher quartiles of IL-6 and C-reactive protein." (PMID 34698811, 2021). "For example, tumour necrosis factor‐α (TNF‐α), interleukin‐6 (IL‐6) and interleukin‐1β (IL‐1β) cause chronic low‐grade inflammation in hypertension." (PMID 34331512, 2021). "It was found that IL-6 levels were positively associated with hypertension and hypercholesterolaemia but negatively associated with triglyceride levels." (PMID 34356982, 2021). "IL-6 levels were found to be associated with dyslipidemia, hypertension, and glucose dysregulation and were associated with poor outcomes in patients with unstable angina or AMI." (PMID 34356982, 2021). "Increased serum levels of CRP, monocyte TNF-α secretion, and serum IL-6 concentrations were reported in patients with hypertension, suggesting a close association between inflammation and hypertension." (PMID 33937238, 2021).
Hypertension (continued). "IL-6 is elevated in hypertension, as well as being associated with a higher incidence of future cardiovascular events and mortality." (PMID 32621022, 2021). "These verdicts suggest that IL-6 is regarded as a pro-inflammatory cytokine that increases the risk for the development of hypertension." (PMID 34806090, 2021). "For example, a previous study demonstrated that hypomethylation of IL-6 gene increases the risk of essential hypertension." (PMID 33971895, 2021). "It has been shown that hypomethylation of IL-6 is related to a higher risk of developing essential hypertension in matched case-control studies with patients and healthy controls of the same ages and gender." (PMID 34806090, 2021). "Pro-inflammatory cytokines such as interleukin-6 (IL-6) have an independent relationship with cardiovascular risk factors, including high blood pressure, reduced high-density lipoprotein cholesterol (HDL-C) levels, and increased body mass index (BMI)." (PMID 33767783, 2021). "In a nested case-control study, interleukin (IL)-6 was less highly related to the risk of developing hypertension than hs-CRP." (PMID 32292598, 2020). "The increase of inflammatory cytokines (TNF-α, IL-2, IL-6 and IL-10) in the serum indicates an increase of systemic inflammation and a risk of hypertension for the mercury-exposed population." (PMID 33083327, 2020). "Plasma levels of lipids, CRP, and IL-6 will be reduced by daily consumption of barberry in patients with hypertension and other cardiovascular risk factors." (PMID 33246500, 2020). "Activation of JAK2/STAT3 induced by Ang-II was totally inhibited by IL-6-deficient mice, showing that Ang-II hypertension is somehow dependent of the increase in IL-6." (PMID 32848763, 2020). "Interleukin-6 (IL-6) is one of the most implicated pro-inflammatory cytokines associated with hypertension." (PMID 31908586, 2019). "p-p38 expression was associated with LPS-induced hypertension and proteinuria excretion, and with increased IL-6 and MCP-1, which were partially reversed by abrogation of p38 activation." (PMID 31507429, 2019). "The major GG genotype in the promoter area of IL-6 -174 G>C was found to be associated with hypertension and increased plasminogen activator inhibitor-1 in Taiwanese." (PMID 30635365, 2019). "The current study demonstrates that hypomethylation of IL-6 promoter was associated with pre-hypertension in young adults." (PMID 31908586, 2019). "Circulating IL-6 affects the endocrine system—it stimulates the hypothalamic–pituitary–adrenal axis, the activation of which is associated with central obesity, hypertension, and insulin resistance." (PMID 31739518, 2019). "If we determined the association of the age-dependent risk factors with cognitive decline per age group, we found that hypertension, high IL-6 levels, and alcohol use were significantly associated with less cognitive decline in the oldest-old subjects." (PMID 30126373, 2018). "Given that IL-6 increases the CRP levels, IL-6 is also likely to act similarly and cause hypertension in patients with PCOS." (PMID 28042549, 2017). "A significant association between plasma IL-6 concentrations and clinical markers of increased arterial stiffness has been reported in patients with hypertension." (PMID 29430085, 2017). "For IL-6 -174 G/C gene polymorphism, the CC genotype was more frequently observed in patients that have associated hypertension (p = 0.05)." (PMID 28852433, 2017). "The goal of this review is to highlight both the cellular and oxidative mechanisms associated with IL-6-signaling in the vascular wall in general, in hypertension, and in response to angiotensin II." (PMID 29186034, 2017). "While there is a clear consensus on the effect of IL-6 deficiency on baseline blood pressure, the effect of IL-6-deficiency on the development of hypertension is much more varied." (PMID 29186034, 2017).
Hypertension (continued). "Increased plasma IL-6 concentrations are significantly associated with a reduced endothelium-dependent vasodilation both in healthy subjects and in patients with hypertension or hypercholesterolaemia." (PMID 29430085, 2017). "There have been reports of adrenal tumors presenting with fever, hypertension, anemia, thrombocytosis, and hyperfibrinogenemia associated with elevated levels of IL-6." (PMID 27579040, 2016). "AngII-induced hypertension is significantly attenuated in IL-6 deficient mice, thus providing evidence that IL-6 is a potent mediator of hypertension in this model." (PMID 26121471, 2015). "Our results have shown that appearance of hypertension in T2D patients with increased body weight was dependent on further increase in IR which was associated with the rise in pro-inflammatory IL-6 cytokine." (PMID 24686488, 2014). "Higher CRP and IL-6 concentrations were associated with increased risk of hypertension in both white and black women." (PMID 25329057, 2014). "Higher IL-6 levels were associated with older age, history of hypertension, higher BMI, and higher homocysteine levels." (PMID 25188448, 2014). "IL-6 was also associated with multiple cardiovascular risk factors (including BMI, hypertension, and smoking)." (PMID 22110481, 2012). "For example, plasma levels of IL-6 are strongly associated with hypertension in humans and can be reduced by administration of Ang II receptor antagonists." (PMID 22269218, 2012). "Essential hypertension seems to be associated with a cytokine pattern biased towards the Th2 system, with an increase of IL-4, IL-7, IL-13, IL-6 and TGF-β, as well as the pro-inflammatory cytokine TNF-α." (PMID 23204981, 2012). "A sustained increase in proinflammatory cytokine IL-6 plasma levels is associated with high blood pressure." (PMID 21410966, 2011). "A G174C polymorphism in the promoter region of the IL-6 gene was shown to be associated with low bone mass in the radius in postmenopausal women and with a high blood pressure and increased CV risk in men." (PMID 21241491, 2011). "Apart from its inflammatory role, IL-1β is a pyrogenic cytokine that in small concentrations induces the production of other cytokines such as IL-6 and can cause hypertension and fever." (PMID 19696895, 2009). "On the other hand, reduced placental IL-6 production has been associated with placental ischemia and failure of fetal growth in pregnancy-induced hypertension." (PMID 18274642, 2007). "Increased renal expression of IL-6 and IL-1b is associated with hypertension." (PMID 41184958, 2025). "Moreover, a higher risk of myocardial infarction has been linked to an increase in IL-6 in hypertension." (PMID 39171117, 2024). "These cytokines, including interleukin-6 and tumor necrosis factor-alpha, can increase the inflammatory burden both locally and systemically, and these markers are closely associated with the development of hypertension." (PMID 39350272, 2024). "Moreover, hypoxia is necessary to encourage a more severe form of pulmonary hypertension, whereas IL-6 overexpression only causes moderate hypertension." (PMID 38193997, 2024). "Furthermore, IL-6, IL-17, ROS, and gut dysbiosis are potential mechanisms underlying comorbid hypertension and anxiety." (PMID 37273529, 2023). "In this study, we investigated whether associations existed between the two promoter hotspot SNPs (rs1800795, -174C > G and rs1800796, -572G > C) in the IL-6 gene and the susceptibility of hypertension in the Chinese population." (PMID 37920615, 2023). "Contrary to the absence of a relationship between IL-1β and the risk for incident hypertension, the same meta-analysis of observational studies demonstrated that higher baseline IL-6 levels are associated with a significant increase in the risk for incident hypertension by 51%." (PMID 36835838, 2023).
Hypertension (continued). "Multiple clinical and epidemiologic studies have demonstrated that many plasma inflammatory markers such as C-reactive protein, high-sensitivity C-reactive protein, interleukin-6 and interleukin-1β are often elevated in patients with hypertension and associated with prognosis." (PMID 36817427, 2023). "Genetic association of IL-6 -174C > G and -572G > C polymorphisms with risk of hypertension." (PMID 37920615, 2023). "Here, we found that daily administration of 10 mg/Kg/day Tac (Tac-10) for 10 days was associated with high blood pressure, an increase in plasma creatinine, and renal damage, represented by the induction in IL-6 and NGAL, two mediators linked to the proinflammatory status." (PMID 37242615, 2023). "Therefore, we sought to examine the association of the two promoter polymorphisms inthe IL-6 gene with essential hypertension (EH) risk among the Chinese population and assess their effects on the IL-6 gene expression levels." (PMID 37920615, 2023). "Similar to our findings, a previous clinical study also indicated that the promoter hypomethylation of the IL-6 gene may enhance essential hypertension risk by upregulating the expression levels of IL-6." (PMID 37920615, 2023). "Pericytes are associated with hypertension in vessels of the lungs of humans and rat models and increase in proliferation preceding hypertension after interaction with the inflammatory cytokine interleukin-6 (IL-6)." (PMID 35634307, 2022). "Therefore, goal of this study was to see if there is alink between IL-6 gene polymorphisms and coronary artery disease with hypertension patients." (PMID 36518119, 2022). "In addition, a borderline association was also found for IL6 polymorphism and both coronary artery disease and hypertension." (PMID 36337884, 2022). "Importantly MMF did not attenuate the development of glomerular fibrosis in Ang II-dependent hypertension, suggesting that glomerular fibrosis is caused by pathological factors other than elevated IL-6 and augmented renal AGT." (PMID 35887028, 2022). "Inflammatory factors such as c-reactive protein and interleukin-6 is increased with prolonged sleep duration, which can cause drowsiness and fatigue, and may also increase the risk of hypertension in people with long sleep duration." (PMID 35064191, 2022). "Many research scholars were interested in the links betweenthe IL-6-572 C/G and IL-6-174 G/C polymorphisms and hypertension, but they couldn't come to conclusion regarding its association with coronary artery disease." (PMID 36518119, 2022). "High salt intake can increase several proinflammatory cytokines, such as interleukin (IL)-6 and IL-23, and may activate TH-17 cells with production of IL-17 and IL-22, which are associated with the development of hypertension." (PMID 35743626, 2022). "Also, chronic infusion of IL-6 in pregnant rats caused hypertension and proteinuria along with reduced vascular relaxation." (PMID 34681861, 2021). "Several genes are associated with vascular disease and hypertension during pregnancy via impaired inflammatory response, hypoxia, and oxidative stress, such as cytokines/chemokines IL-1β, IL-6, IL-8, and impairment expression in endothelial cells/VSMCs of HIF1α and eNOS genes." (PMID 34867473, 2021). "In an effort to understand the mechanisms by which the elevation of IL-6 cytokine family members may cause renal damage, an angiotensin II infusion mouse model of hypertension and CKD was used." (PMID 30871285, 2019). "At the other end of the spectrum, IL-6-deficient mice have been used in a number of studies examining the effect of IL-6-deficiency on both baseline blood pressure and on the development of hypertension." (PMID 29186034, 2017). "However studies have demonstrated that the activation of AT1 receptor appears to mediate hypertension associated with excessive IL-6 during preE." (PMID 28492503, 2017).
Hypertension (continued). "Furthermore, prospective evidence demonstrates an association between IL-6 reactivity to stress and the development of subclinical hypertension." (PMID 26943141, 2016). "Besides its BP-lowering effect, we found that Eplerenone also significantly decreased the plasma concentrations of resistin and IL-6, both of which have been associated with inflammation and hypertension in obesity." (PMID 27032687, 2016). "Indeed, IL-6 has been detected in atherosclerotic plaques, and prolonged elevation of IL-6 is strongly associated with increased levels of cholesterol and hypertension." (PMID 23782265, 2013). "A growing body of evidence suggests a close association of IL-6 level and hypertension in patients." (PMID 22574112, 2012). "Because inflammation plays an important role in myocardial remodeling in response to hypertension and exogenous IL-6 may cause myocardial fibrosis, we examined the effect of endogenous IL-6 on Ang II-induced cardiac fibrosis." (PMID 22574112, 2012). "Hypertension significantly modified the association of IL-6 SNPs with LOAD risk." (PMID 22272811, 2012). "In addition, hypertension significantly modified the association of IL-6 polymorphisms with LOAD risk." (PMID 22272811, 2012). "Among the vascular risk factors explored in this study (e.g., hypertension, type 2 DM, and hyperlipidemia), hypertension was the only factor that significantly modified the association between IL-6 SNPs and risk of LOAD (SNP2: pinteraction = 0.03 under dominant model)." (PMID 22272811, 2012). "Additionally, research indicates that hypertension-induced alterations in cognitive function may be associated with the disruption of the blood-brain barrier and imbalances in angiotensin II, interleukin-6 (IL-6), and interleukin-17 (IL-17)." (PMID 39543520, 2024). "In the present study, our results showed that frequencies of genotypes bearing the C allele of IL-6 rs1800795 (-174C > G) were only found in patients with hypertension enabling us to conjecture that the presence of the G allele might be protective against the progression to hypertension." (PMID 37920615, 2023). "Thus, IL-6 is part of the pro-inflammatory phenotype that is associated with hypertension." (PMID 35885053, 2022). "On the other hand, IL6 appeared to be a link mechanism between cancer and inflammatory pathogenic mechanisms because it was found associated with lung inflammation, lung fibrosis, hypertensive disease, myocardial ischemia, pathways in cancer, lung neoplasms, and neoplasm invasiveness." (PMID 34440025, 2021). "However, the mechanisms by which inflammatory markers other than hs-CRP and IL-6 are related to hypertension risk remain unclear." (PMID 32292598, 2020). "Thus, IL-6 methylation could be used as an early indicator for predicting hypertension and related risk of cardiovascular diseases in prehypertensive subjects." (PMID 31908586, 2019). "In particular, SPE patients had elevated levels of IL-6 in serum, a cytokine that is widely implicated in systemic inflammation and associated with hypertension; in fact, several animal models have shown that IL-6 is one of the mediators of hypertension under hypoxic conditions in the placenta." (PMID 25574467, 2014). "Furthermore, angiotensin II-associated hypertension was attenuated in interleukin-6 knockout mice." (PMID 23844114, 2013). "However, this association was lost after adjustment for age, gender, race, hypertension, and the inflammatory marker IL-6 (relative risk for the prevalence of CAC was 1.03 [95% confidence interval 0.98 to 1.08] for GFR below compared with above 60 m/min per 1.73 m2)." (PMID 21311747, 2011). "Leptin, IL-6, and VEGF presented the strongest correlation with hypertension, suggesting their potential in future diagnostic and preventive strategies." (PMID 41596212, 2026). "Interleukin-6 has been identified in animal studies as a key mediator in angiotensin II (Ang II)-induced hypertension." (PMID 40422564, 2025).